RLN2 (relaxin 2)
Diseases named in the same sentence as RLN2 in open-access papers (continued):
Sharing a sentence is not in itself a finding about the gene and the disease.
tumor (continued). "We can hypothesize that although preclinical studies indicate that RLN2 may actively influence the tumor microenvironment through angiogenesis, ECM remodeling, and modulation of stromal cells, these mechanisms are primarily localized processes." (PMID 41373753, 2025). "It has also been shown that RLN2 may play a role in angiogenesis and extracellular matrix remodeling, which may be important in tumor progression." (PMID 41373753, 2025). "RLN2 may enhance the antitumor activity of CAR-T cells against solid tumors by promoting their infiltration into the tumor microenvironment." (PMID 40666525, 2025). "Relaxin-2 stained some chondrocytes and osteocytes in the cartilage and bone tissue underlying and remote from the tumor, whereas there was no staining in either the cartilaginous or bone matrix." (PMID 35562926, 2022). "The serum levels of RLN2 in both tumor types were under the detection limit (≤7.8 pg/mL)." (PMID 34440475, 2021). "Our previous study also found RLN2 was related with OS tumor growth, neovascularization, metastasis, and oncogenic progression, but the underlying molecular mechanisms of this action are largely unknown." (PMID 26229955, 2015). "However, in vivo prostate xenograft tumor RLN2 inhibited pro-MMP-9 expression, which was opposite to our study." (PMID 26229955, 2015). "It reduced the MG-63 tumor vasculature, the new blood vessel formation was significantly reduced in MG-63 tumor by anti- relaxin-2 mAb in the intervention model (80% inhibition), which suggested that relaxin-2 blockage inhibits tumor growth by in part inhibition of angiogenesis." (PMID 23758748, 2013). "Furthermore, we analyzed the tumor tissues from control and anti- relaxin-2 mAb groups for relaxin using Western blot assay." (PMID 23758748, 2013). "Having shown that relaxin-2 knockdown with siRNA decreased invasion and angiogenesis in MG-63 cells in vitro, we tested the growth of the tumors accomplished by anti- relaxin-2 mAb on tumor growth in nude mice." (PMID 23758748, 2013). "We observed significant expression levels of relaxin-2 in control tumor sections." (PMID 23758748, 2013). "Furthermore, correlation analysis revealed only a weak relationship between RLN2 levels and tumor stage, suggesting that if RLN2 contributes to colorectal cancer progression, its effect is likely minor or indirect and mediated through other biological pathways." (PMID 41373753, 2025). "In conclusion, RLN2 secreted by engineered CAR-T cells demonstrated specific MMP-inducing capabilities, promoted collagen degradation in vivo, and improved tumor suppression in xenograft models with abundant stroma." (PMID 40666525, 2025). "In mouse xenograft models with abundant stromal content, RLN2-secreting CAR-T cells demonstrated significantly improved antitumor efficacy and infiltration into the tumor microenvironment compared to conventional CAR-T cells." (PMID 40666525, 2025). "Therefore, the primary aim of this study was to evaluate the diagnostic usefulness of serum RLN2 and YKL-40 as biomarkers in patients with colorectal cancer, compared to conventional ones (CEA and CA19-9), while the secondary aim was to explore their associations with tumor stage and therapy." (PMID 41373753, 2025). "RLN2 expression is found to be up-regulated in HCC tissues, which can be taken as a predictor for tumor progression and adverse prognosis." (PMID 30705088, 2019). "Only in 1 cell was there found a gain of the chromosomal region 9p24.3–9p23, where PTPRD is located, which has been reported to act like a tumor suppressor gene in NB, in addition to other genes, indicated to be related to cancer (i.e., JAK2, RLN2, TYRP1)." (PMID 30791380, 2019). "Oligonucleotide primers employed at melting temperatures (TM in °C) used to determine the expression of RLN2, human RXFP1 relaxin receptor (RXFP1), S100A4 and 18S transcripts in human breast cancer cell lines and xenograft tumours." (PMID 18718015, 2008).
tumor (continued). "Xenograft tumour tissues were assessed by histology and immunohistochemistry and frozen tissues were used for the detection of S100A4 and RLN2." (PMID 18718015, 2008). "This may enable RLN2-secreting CAR-T cells to penetrate the stromal barrier and more efficiently reach SU86.86 cells at the tumor site." (PMID 40666525, 2025). "We evaluated the efficacy of RLN2-secreting CAR-T cells in these models however, observed that RLN2 secretion did not enhance antitumor activity in either tumor model (right)." (PMID 40666525, 2025). "Following treatment with RLN2-secreting CAR-T cells, type IV collagen expression in the tumor was significantly reduced by RLN2-induced MMP-9 and MMP-7 expression, potentially facilitating easier contact between the extravasated CAR-T and cancer cells after traversing the interstitial stroma." (PMID 40666525, 2025). "Importantly, RLN-2 appears to play a dual role depending on tissue context: in healthy tissues, it can exert protective and pro-regenerative effects, whereas in certain tumor microenvironments, its immunosuppressive actions might inadvertently favor tumor growth." (PMID 41196672, 2025). "However, expression levels were drastically reduced in the tumor sections of mice treated with anti- relaxin-2 mAb (data not shown)." (PMID 23758748, 2013).
cancer (9 papers, 2013 to 2025). A tumor composed of atypical neoplastic, often pleomorphic cells that invade other tissues. "Most recently relaxin-2 has been associated with cancer biology." (PMID 23758748, 2013). "We believe that our approach utilizing RLN2 to overcome the stromal barriers hindering CAR-T cell delivery to cancer cells represents a significant advancement in pancreatic and biliary cancer therapies, the efficacies of which have been limited." (PMID 40666525, 2025). "Both YKL-40 and CA19-9, as well as RLN2, correlated weakly but positively with cancer stage, suggesting their partial usefulness as indicators of progression." (PMID 41373753, 2025). "In vitro studies revealed that cancer cells exposed to CAR-T cell-secreted RLN2 exhibited an increased expression and secretion of specific matrix metalloproteinases." (PMID 40666525, 2025). "Given this dual function, the molecular mechanism behind relaxin-2's effect in cancer appears unclear, and more research to clarify its possible role as a cancer-preventative factor is of utmost relevance." (PMID 37900385, 2023). "Relaxin-2 plays a crucial function in many malignancies, as evidenced by the pro- and antitumor effects observed in various malignant tumors." (PMID 37900385, 2023). "Both our in vitro analysis and previous report demonstrated that RXFP1 had a crucial role in RLN2-induced cancer invasion." (PMID 30126180, 2018). "RXFP1 immunoreactivity was detected in the cytoplasmic membrane of carcinoma cells, and RLN2 immunoreactivity was detected in the cytoplasm of carcinoma cells." (PMID 30126180, 2018). "Similar to relaxin-2 mRNA, serum relaxin-2 were significantly higher in advanced stage cancer and hematogenous metastasis cancer." (PMID 23758748, 2013). "Previous studies have shown that knockdown of relaxin-2 inhibited invasion and angiogenesis in cancer cells in vitro." (PMID 23758748, 2013). "Relaxin-2 mRNA and serum relaxin-2 were significantly higher in advanced stage cancer and hematogenous metastasis cancer." (PMID 23758748, 2013). "By preferentially degrading collagen type IV, in addition to collagen type I and III fibers, RLN2 overcomes the stromal barrier, enabling RLN2-secreting CAR-T cells to reach cancer cell nests and potentially enhance their cytolytic activity and antitumor efficacy." (PMID 40666525, 2025). "Reports have indicated that introducing RLN2 into cancer cells may suppress fibrosis within tumors by modulating macrophage polarization, thereby enhancing cytotoxic T cell infiltration and immune checkpoint inhibitor efficacy." (PMID 40666525, 2025). "RLN2 demonstrates promising characteristics for use in cancer therapy." (PMID 40666525, 2025). "The incidence of advanced stage cancer and hematogenous metastasis cancer in the high relaxin-2 mRNA expression group and high serum relaxin-2 levels groups was significantly higher than that in the low relaxin-2 expression group and low serum relaxin-2 levels groups, respectively." (PMID 23758748, 2013). "Additional functions of relaxin-2, such as stimulation of angiogenesis, might have also contributed to cancer growth." (PMID 23758748, 2013). "In the conventional CAR-T cell group, cancer clusters remained intact, whereas they were disrupted in the RLN2-secreting CAR T-cell group, leading to a reduction in the number of cancer cells." (PMID 40666525, 2025). "qPCR analyses revealed that RLN2-secreting CAR-T cells, particularly activated cells, induced MMP-2 and MMP-9 expression, though at lower levels than that in cancer cells, suggesting that the primary mechanism of stromal dissolution by RLN2-secreting CAR-T cells is paracrine, acting on cancer cells." (PMID 40666525, 2025). "Notably, RLN2-secreting CAR-T cell therapy demonstrated potent antitumor efficacy in SU86.86 xenograft tumors, overcoming resistance by breaching the stromal barrier and effectively targeting cancer cells." (PMID 40666525, 2025).
cardiovascular diseases (4 papers, 2018 to 2024). "It is hypothesized that endogenous relaxin-2 could act as a physiologic agent with a relevant role as a natural protector against cardiovascular disease." (PMID 35887517, 2022). "Since serelaxin (RLX030) represents the recombinant form of human relaxin-2, which shows quite reliable therapies in cardiovascular diseases, we are aimed to identify the function and mechanisms of RXFP1signaling pathways utilized by human relaxins in the vasculature." (PMID 30233409, 2018).
diseases of the heart (2 papers, 2022 to 2023). "Relaxin-2 is known to have anti-fibrotic and anti-inflammatory properties in diseases of the heart, liver and kidney." (PMID 37545557, 2023). "In patients with HF with reduced ejection fraction (HFrEF), plasmatic relaxin-2 concentrations could be four- to six-fold higher in moderate HF (class II NYHA), and twelve- to sixteen-fold higher in severe HF (class IV NYHA), when compared with individuals without heart disease." (PMID 35887517, 2022).
lung (2 papers, 2013 to 2020). "We showed that relaxin-2 (relaxin) exerts a protective effect in lung IR, attributable to decreases in endothelin-1 (ET-1) production, leukocyte recruitment, and free radical generation." (PMID 24098703, 2013).
gastrointestinal disease (1 paper, 2025). A disease that occurs in the gastrointestinal system, excluding the hepatobiliary system. "This study highlights that targeting the MMP9/RLN2 signaling axis presents a promising approach to developing new strategies for UC treatment and other related gastrointestinal diseases." (PMID 40529132, 2025).
kidney disease (1 paper, 2023). "In conclusion, our study has established that delivery of relaxin-2 mRNA to kidneys cells is a novel treatment for suppressing the progression of kidney disease." (PMID 37545557, 2023). "Our in vivo experiment validated relaxin-2 mRNA as a therapeutic strategy for kidney disease." (PMID 37545557, 2023).
RLN2 also shares sentences with these, for which no sentence is quoted: Arrhythmia (2 papers); Hypertension (2); Anxiety (1); autoimmune disease (1); chronic heart failure (1); endometriosis (1); esophageal cancer (1); glioblastoma (1); hypertriglyceridaemia (1); hypertrophic cardiomyopathy (1); injury (1); ischemic stroke (1); metabolic syndrome (1); myeloma (1); neuroblastoma (1); renal carcinoma (1); rheumatoid arthritis (1); systemic lupus erythematosus (1); systemic sclerosis (1); thyroid (1); type 2 diabetes (1); ulcerative colitis (1).